HELLPAR (HELLP associated long non-coding RNA)
Synonyms: LINC-HELLP
Gene: Long non-coding RNA gene on chromosome 12 (102,197,585 to 102,402,596, forward strand). Ensembl gene ENSG00000281344.
Gene Ontology:
Biological process: SRP-dependent cotranslational protein targeting to membrane, signal sequence recognition
Cellular component: signal recognition particle, endoplasmic reticulum targeting
Diseases named in the same sentence as HELLPAR in open-access papers:
HELLPAR is named in the same sentence as 9 diseases in open-access papers, as found by Europe PMC text mining. Sharing a sentence is not in itself a finding about the gene and the disease. The quoted sentences say what the papers report.
HELLP syndrome (2 papers, 2021 to 2022). A life-threatening condition that can potentially complicate pregnancy. "Mutations in the LINC-HELLP non-coding RNA (HELLPAR) have been associated with familial forms of the pregnancy-specific HELLP syndrome." (PMID 34095140, 2021).
glioma (1 paper, 2023). A benign or malignant brain and spinal cord tumor that arises from glial cells (astrocytes, oligodendrocytes, ependymal cells). "And through multiple analysis, the good predictive performance of HELLPAR/RRM2 axis for gliomas patients was confirmed." (PMID 36750807, 2023). "A time-dependent ROC analysis of HELLPAR expression in glioma patients suggested that HELLPAR may accurately predict glioma patients' prognosis at 1, 3, and 5 years." (PMID 36750807, 2023). "Although studies have shown that HELLPAR affects the transition of the extravillous trophoblast (EVT) from a proliferative to an invasive state, the role of HELLPAR in glioma has not been reported and further experiments are needed to verify its specific function." (PMID 36750807, 2023).
non-small cell lung carcinoma (1 paper, 2017). A group of at least three distinct histological types of lung cancer, including non-small cell squamous cell carcinoma, adenocarcinoma, and large cell carcinoma. "Other identified lncRNAs included LUCAT1, which is important in non-small cell lung cancer, NEAT1, and HELLPAR." (PMID 28957348, 2017).
pancreatic cancer (1 paper, 2022). "No study is available that characterized the functional significance of HELLPAR in cancer progression although a previous study proposed a potential role of HELLPAR as a ceRNA of miR‐30d‐5p and a regulator of the miR‐30d‐GJA1 signaling axis in pancreatic cancer." (PMID 35612714, 2022).
prostate tumors (1 paper, 2022). "Expression analysis of HELLPAR RNA in prostate tumors (ntumor = 24) and matching uninvolved tissues (nnormal = 24) by qRT‐PCR using primer set #1 showed an upregulation (1.7‐fold) of HELLPAR in tumor tissues compared to uninvolved areas." (PMID 35612714, 2022).
tumor (2 papers, 2022 to 2023). "Our results contribute to understanding the regulatory behavior of lncRNAs in mCRPC and indicate SNHG18 and HELLPAR as master regulators and potential new diagnostic targets in this tumor." (PMID 37644825, 2023). "Analysis of the xenograft tumor tissues also showed significant downregulation of HELLPAR in the doxycycline‐treated groups (~ 0.38‐fold and ~ 0.2‐fold) compared to the uninduced control groups." (PMID 35612714, 2022).
HELLPAR also shares sentences with these, for which no sentence is quoted: prostate carcinoma (2 papers); cancer (1); lung adenocarcinoma (1).